ADAM9 (ADAM metallopeptidase domain 9)
Diseases named in the same sentence as ADAM9 in open-access papers (continued):
Sharing a sentence is not in itself a finding about the gene and the disease.
pancreatic cancer (34 papers, 2004 to 2026). "To characterize functionally the role of ADAM9 in pancreatic cancer, we generated a stable loss of function systems in two established PDAC cell lines, AsPC‐1 and MiaPaCa‐2." (PMID 30556643, 2019). "ADAM9 and PAK2 showed high expression in pancreatic cancer and strong associations with tumor proliferation, invasion, and immune regulation." (PMID 42131338, 2026). "Consistent with our findings, PKC activation was reported to induce ADAM9 upregulation in NSCLC cells, and NF-κB signaling was shown to promote ADAM9 expression in pancreatic cancer." (PMID 40113769, 2025). "ANO1, AHNAK2, and ADAM9 were eventually identified as feature genes of pancreatic cancer, helping to diagnose and predict prognosis." (PMID 37170188, 2023). "The results showed that only three feature genes—ANO1, AHNAK2, and ADAM9, were significantly associated with prognosis in all three analyses (p < 0.05), which means that these three feature genes may act as molecular markers for predicting the prognosis of pancreatic cancer patients." (PMID 37170188, 2023). "There have been many studies on ADAM9 and tumors, it has been found that circ-ADAM9 also showed an upward regulatory trend in pancreatic cancer." (PMID 37170188, 2023). "The present study indicated that ITGA2, ITGA3, ADAM9, and BHLHE40 were potential target genes associated with the development of pancreatic cancer." (PMID 37377917, 2023). "ADAM9, has been previously reported to be upregulated in pancreatic cancer, and high ADAM9 expression in PDAC has been correlated with poor patient survival." (PMID 35052825, 2022). "For example, ADAM9 is involved in tumor cell metastasis, proliferation, angiogenesis and immune evasion and high levels of ADAM-9 in pancreatic cancer is associated with short OS and higher tumor grade and progression." (PMID 33648511, 2021). "More importantly, it was found that pancreatic cancer patients with high expression of circ-ADAM9 had poorer survival rate than those with low expression of circ-ADAM9." (PMID 34439315, 2021). "In a study on 58 patients with pancreatic cancer, high expression of circ-ADAM9 was found in pancreatic cancer tissues with advanced clinical stage and lymph node metastasis." (PMID 34439315, 2021). "In recent years, several studies have suggested that elevated mRNA expression of ADAM9 shortens the overall survival of pancreatic cancer patients, a finding that was confirmed by immunohistochemistry." (PMID 33096780, 2020). "Studies have demonstrated that circular ADAM9 (circ-ADAM9) is up-regulated in pancreatic cancer cells and is correlated with poor prognosis." (PMID 33096780, 2020). "Experiments have reported that through the analysis of mRNA expression levels in micro-dissected pancreatic cancer specimens, ADAM9 overexpression was found in pancreatic tumor cells." (PMID 32875951, 2020). "Overexpressed ADAM9 was found in cancers including esophageal squamous cell carcinoma, pancreatic cancer, prostate cancer, and breast cancer." (PMID 32637415, 2020). "Tumor suppressive miR-126 and its target ADAM9 play role in controlling migration and invasion in pancreatic cancer." (PMID 32489562, 2020). "Upregulation of a disintegrin and metalloprotease 9 (ADAM9) is correlated with progression of cancers, such as prostate, bladder, and pancreatic cancers." (PMID 32637415, 2020). "MiR-126-3p also interact with malignant cells by inhibiting ADAM9 (disintegrin and metalloproteinase domain-containing protein 9) in pancreatic cancer." (PMID 31533317, 2019). "Overexpression of ADAM9 has been found in thyroid cancer and other cancers, including breast cancer, hepatocellular carcinoma, pancreatic cancer, prostate cancer, and melanoma." (PMID 26244545, 2015). "Expression of miR-126 and ADAM9 were mutually exclusive, and re-expression of miR-126 attenuated pancreatic cancer cell migration and invasion." (PMID 22934011, 2012).
pancreatic cancer (continued). "Database analysis identified that miR-126 potentially targets disintegrin and metalloproteinase domain-containing protein 9 (ADAM9), which is highly expressed in pancreatic cancer." (PMID 22934011, 2012). "Among the pancreatic tumours, that is neoplasms of the acinar, endocrine and ductal phenotype, ADAM9 expression was selective for PDACs." (PMID 14997207, 2004). "In addition, several ncRNAs such as AFAP1-AS1, UCA1, HOTAIR, PVT1, MALAT-1, circ-ADAM9, BC008363, circ-LDLRAD3, circ-IARS, circ-PDE8A, circ_0030235, and circ_0001649 have been associated with prognosis of pancreatic cancer." (PMID 34439315, 2021). "ADAM9 is also regulated by various miRNAs in pancreatic cancer." (PMID 33096780, 2020). "To investigate the role of ADAM9 in pancreatic cancer in vivo, we chose an orthotopic murine model." (PMID 30556643, 2019). "Furthermore, interactions of miR-126 and ADAM9 are related to epithelial-mesenchymal transition and the invasive growth of pancreatic cancer cells." (PMID 26351404, 2015). "This study was designed to further validate the significance of ADAM9 overexpression in PDACs by comparing the results with those obtained in pancreatic tumours other than PDACs, and by correlating the immunohistochemical labelling of the individual PDACs with the survival of the patients." (PMID 14997207, 2004). "Additionally, ADAM9 was shown to stabilize mutant KRAS in pancreatic cancers." (PMID 40429751, 2025). "A previous study conducted in relation to pancreatic cancer, where EMT is considered a prognostic factor as it is in bladder cancer, suggested that ADAM9 knockdown attenuated cellular migration in Panc-1 and ASPC-1 cells." (PMID 35740916, 2022). "Overexpressing circ-ADAM9 increases ERK signaling to promote cell proliferation and migration in vitro, and silencing circ-ADAM9 delays pancreatic tumor growth in vivo." (PMID 33096780, 2020). "We probed the effect of ADAM9 expression silencing on the sensitivity of PDAC cell lines to gemcitabine, a standard mode of treatment for pancreatic cancer." (PMID 30556643, 2019). "Although there were no ADAM9 images, previous literature have confirmed that ADAM9 was high protein expression in pancreatic cancer samples and promoted the development of pancreatic cancer." (PMID 37170188, 2023). "In addition to protein levels, NSD3 induces global H3K36 dimethylation in pancreatic cancer cells and influences the mRNA levels for genes including ADAM28, ADAM9, BIRC3, CXCL5, DUOX2, GABRP, ITGB6, and RAB11FIP1." (PMID 37062069, 2023). "IMGC936 (an anti-ADAM9 antibody drug conjugate developed by MacroGenics) is undergoing Phase 1 investigations involving patients with TNBC, nonsquamous non-small cell lung cancer, colorectal cancer, gastroesophageal cancer, or pancreatic cancer (NCT04622774)." (PMID 36778124, 2023). "Hence, our systematic analysis not only proposed amplification of ADAM9 which could be utilized as a biomarker for PDAC metastasis, but also offered support for the utilization of SRC inhibitor (Bosutinib) in the treatment of pancreatic cancer." (PMID 36434634, 2022).
prostate carcinoma (32 papers, 2004 to 2026). A carcinoma that arises from epithelial cells of the prostate gland. "A disintegrin and metalloproteinase 9 (ADAM9) encoded protein regulates prostate cancer proliferation and invasion by interacting with a variety of cell surface proteins in prostate cancer." (PMID 33489872, 2020). "Loss of ADAM9 in prostate cancer cells results in the impairment of proliferation and the osteolytic reaction, as well as causing G1/G0 cell cycle arrest." (PMID 23342005, 2013). "Moreover, we have identified that TMEFF2 is also a novel substrate for other proteases implicated in prostate cancer, including two ADAMs (ADAM9 and ADAM12) and the type II transmembrane serine proteinases (TTSPs) matriptase‐1 and hepsin." (PMID 28762604, 2018). "Additionally, ADAM9 protein expression was also reported to be significantly associated with shortened prostate-specific antigen relapse-free survival in prostate cancer." (PMID 27571068, 2016). "In summary, ARD1's role in prostate cancer is intertwined through multiple mechanisms, including the acetylation and nuclear translocation of AR and its interaction with ADAM9." (PMID 40026288, 2025). "Among ADAMs, ADAM9, -10, -12, -15, -19, and -28 were suggested to have biomarker potential in prostate cancer." (PMID 38255186, 2023). "Examples of those are ADAM15, -17, and -28, with mainly consistent literature, and ADAM9, with more complex involvement in prostate cancer." (PMID 38255186, 2023). "Suppression of migration by ADAM9 knockdown has been reported in the PC3 prostate cancer cell line used to study cell adhesion, spreading, and migration, and in breast cancer." (PMID 35740916, 2022). "Studies have shown that when human prostate cancer cells are exposed to stress conditions such as cell crowding, hypoxia and hydrogen peroxide, the expression levels of ADAM9 mRNA and protein also increase." (PMID 32875951, 2020). "The underlying mechanism of ADAM9 in prostate cancer has also been discovered: ADAM9 can cleave and release epidermal growth factor and FGFR2iiib from cells, both of which play a key role in the pathogenesis of prostate cancer." (PMID 32875951, 2020). "For prostate cancer cells, ADAM9 is likely to be responsible for supporting its survival and tumor progression." (PMID 32875951, 2020). "Several of these genes are important for prostate cancer progression including metalloproteinases ADAM9 and ADAM10." (PMID 32365491, 2020). "In summary, these results reveal that ADAM9 is involved in the possible pathogenesis of prostate cancer, and also indicate that ADAM9 is likely to become a good target for anti-tumor drugs in the future." (PMID 32875951, 2020). "(2011) investigated the sensitivity of C4‐2 prostate cancer cells to a panel of chemotherapy drugs (doxorubicin, docetaxel, etoposide, cisplatin, and gemcitabine) upon ADAM9 silencing." (PMID 30556643, 2019). "ADAM9 expression is significantly higher in prostate cancer tissue than normal prostate tissue and inhibition of ADAM9 expression in prostate cancer enhanced prostate cancer sensitivity to radiation and chemotherapy." (PMID 26912236, 2016). "ADAM9 is typically regarded as oncogene in many cancers, such as oral squamous cell carcinomas, breast tumors, prostate cancer, and renal cell cancer." (PMID 24705471, 2014). "In the present study, we assess the feasibility of lentiviral vector-delivered small hairpin RNA (shRNA) against ADAM9 for the treatment of androgen-independent and bone metastatic human prostate cancer in an experimental animal model." (PMID 23342005, 2013). "A similar result was also obtained with subcutaneous xenografts, which indicated an important role of ADAM9 in prostate cancer cell proliferation and tumor growth." (PMID 23342005, 2013). "Previous work done by our group and others have shown in clinical studies that higher ADAM9 levels correlate with a shorter period of prostate cancer remission." (PMID 23342005, 2013).
prostate carcinoma (continued). "Microarray data showed significantly decreased levels of regenerating islet-derived family member 4 (REG4) expression in prostate cancer cells with knockdown of ADAM9 gene expression." (PMID 23342005, 2013). "We also show, for the first time that ADAM9 knockdown induces cell cycle arrest at the G1/S transition in prostate cancer cells under serum starvation conditions." (PMID 23342005, 2013). "Our data reveal a novel molecular mechanism of ADAM9 in the regulation of prostate cancer cell proliferation, and suggests a combined modality of ADAM9 shRNA gene therapy and cytotoxic agents for hormone refractory and bone metastatic prostate cancer." (PMID 23342005, 2013). "Several lines of studies in other cancer types have demonstrated an impact of REG4 on tumor growth, invasion, metastasis, and resistance to apoptosis, which is similar to the role of ADAM9 in prostate cancer seen in the previous and the present studies." (PMID 23342005, 2013). "In the present study, we demonstrated the ability of ADAM9 shRNA impaired androgen-independent prostate cancer PC3 tumor formation and cancer-induced osteolysis in a skeletal metastasis xenograft model." (PMID 23342005, 2013). "This may be novel because there was no animal study using a neutralizing antibody for sADAM9 to see the relationship between ADAM9 expression and prostate cancer." (PMID 38928352, 2024). "A disintegrin and metalloproteinase domain-containing protein 9 (ADAM9) functions as a membranous bridge, forming cell-cell and cell-matrix connections that regulate tumor aggressiveness in various cancer types, including prostate cancer (PCa)." (PMID 39628685, 2024). "In prostate cancer, ADAM9 cleaves insulin β-chain, tumor necrosis factor (TNF)-α, transforming growth factor (TGF)-α, gelatin, β-casein, etc., and induces the shedding of epidermal growth factor (EGF), fibroblast growth factor receptor 2 (FGFR2)-IIIB and heparin-binding EGF-like growth factor." (PMID 35740916, 2022). "In ADAM9‐silenced prostate cancer cells, the expression levels of integrin β1 was up‐regulated, whereas the activity of integrin β1 at cell surface was damaged and the formation of focal adhesions was delayed, probably explaining the reduction in cell adhesion and migration." (PMID 33811456, 2022). "Previous studies showed positive nuclear staining of ADAM9 and its association with lethal phenotypic progression of prostate cancer 37, but the role and regulation of nuclear ADAM9 has not been elucidated." (PMID 34671207, 2021). "It has been established that ADAM9 protease (ADAM family) takes part in the processes of cell adhesion, migration, and signaling; overexpression of ADAM9 has been described in many solid tumors, such as cancer of the prostate, kidney, pancreas, lungs, and stomach." (PMID 34830452, 2021). "Further investigation of the correlation between ADAM9 and REG4 may help to understand the underlying mechanism of therapy-resistance in prostate cancer." (PMID 33489872, 2020). "MiRNAs also play a role in regulating ADAM9 in prostate cancer, especially miR-126." (PMID 33096780, 2020). "ADAM9 regulates prostate cancer progression and outcome in other ways as well." (PMID 33096780, 2020). "In the process of prostate cancer, ADAM9 and ROS are accompanied, which may involve a kind of stress." (PMID 32875951, 2020). "Because the expression of ADAM9 is reduced, prostate cancer cells will undergo apoptosis." (PMID 32875951, 2020). "Since the EGFR has been reported to promote prostate cancer metastasis to bone by down-regulating miR-1, we further investigated whether ADAM9 may suppress miR-1 expression by activating EGFR signaling." (PMID 28537886, 2017). "Inhibition of ADAM9 expression can sensitize prostate cancer cells to radiation and chemotherapy." (PMID 24705471, 2014).
prostate carcinoma (continued). "To validate the role of ADAM9 in prostate cancer progression, we stably downregulated ADAM9 expression in androgen-independent, bone metastatic PC3 prostate cancer cells and androgen-dependent LNCaP prostate cancer cells with either retroviral or lentiviral vectors carrying ADAM9-specific shRNA." (PMID 23342005, 2013). "For example, ADAM9 promotes the invasion and metastasis of cancer cells in melanoma by activating MMP1 and MMP2, while ADAM17 can activate MMP2 to treat the disease (prostate cancer and lung injury) by promoting angiogenesis." (PMID 36172139, 2022). "In prostate cancer, Vimentin, N-cadherin, and E-cadherin fluctuated in a manner suggesting the suppression of EMT via regulation of ADAM9." (PMID 35740916, 2022). "Given that knockdown ADAM9 decreases the expression of REG4, we suggest a regulatory role of ADAM9 in REG4-mediated prostate cancer progression." (PMID 23342005, 2013). "Overexpression of ADAM species is known in tumor cell lines, for example, ADAM10, ADAM12 and ADAM15 in hematological malignant tumor cell lines, and ADAM9, ADAM10, ADAM15 and ADAM17 in prostate cancer cell lines." (PMID 16277668, 2005). "ADAM9, a member of the ADAM family that is involved in various biological processes, was found to be overexpressed in prostate carcinoma cell lines, hepatocellular carcinoma and breast carcinoma." (PMID 14997207, 2004). "ADAM9 expression gradually increases in cancer tissue and is recognized as a negative prognostic biomarker for prostate cancer patients." (PMID 37383726, 2023). "As with ADAM17 in breast cancer, the prognostic impact of ADAM9 in prostate cancer was independent of the conventionally used factors for this malignancy such as tumour size, Gleason grade and preoperative PSA level." (PMID 21906355, 2011).